ZNF732 (zinc finger protein 732)
Description:
May be involved in transcriptional regulation.
Synonyms: FLJ59067
Tractability: PROTAC: ubiquitination databases record sites on it.
Gene: Protein-coding gene on chromosome 4 (270,675 to 305,474, reverse strand). Ensembl gene ENSG00000186777.
Subcellular location: Nucleus
Pathways (Reactome):
Gene expression (Transcription): Generic Transcription Pathway
Gene Ontology:
Molecular function: DNA-binding transcription factor activity, RNA polymerase II-specific; RNA polymerase II cis-regulatory region sequence-specific DNA binding; double-stranded DNA binding
Biological process: regulation of DNA-templated transcription; negative regulation of transcription by RNA polymerase II
Cellular component: nucleus
Genetic constraint (gnomAD): Loss-of-function variants: 14 observed, 13.31 expected, observed/expected ratio (o/e) 1.05, 90% interval 0.69 to 1.62. The upper end of that interval is the gene's LOEUF score, 1.62, which puts it in group 6 of 6, group 1 being the genes least tolerant of losing a copy. Missense variants: 702 observed, 673.27 expected, observed/expected ratio (o/e) 1.04, 90% interval 0.98 to 1.11. Synonymous variants: 231 observed, 234.62 expected, observed/expected ratio (o/e) 0.98, 90% interval 0.88 to 1.1.
Homologues: Orthologues: chimpanzee ZNF732 (98% identical). Paralogues in human: ZNF595 (70% identical), ZNF141 (63% identical), ZNF493 (62% identical), ZNF726 (56% identical), ZNF728 (56% identical), ZNF254 (55% identical), ZNF724 (55% identical), ZNF708 (55% identical), ZNF718 (54% identical), ZNF43 (54% identical), ZNF93 (54% identical), ZNF429 (53% identical), and 164 more.
Diseases named in the same sentence as ZNF732 in open-access papers:
ZNF732 is named in the same sentence as 3 diseases in open-access papers, as found by Europe PMC text mining. Sharing a sentence is not in itself a finding about the gene and the disease. The quoted sentences say what the papers report.
meningioma (1 paper, 2020). A generally slow growing tumor attached to the dura mater. "Besides, potential roles of ABCA11P, ZNF732, and ZNF876P are novel in meningioma recurrence." (PMID 32923390, 2020).
ZNF732 also shares sentences with these, for which no sentence is quoted: cancer (1 paper); head and neck squamous cell carcinoma (1).